GCG (glucagon)
Diseases named in the same sentence as GCG in open-access papers (continued):
Sharing a sentence is not in itself a finding about the gene and the disease.
Hypoglycemia (continued). "There are mainly three ways to rescue for hypoglycemia: mathematically minimizing the SC accumulation, suspending the insulin delivery (termed as prediction/suspending solution), and using glucagon as a counterregulatory agent in closed-loop system." (PMID 24260042, 2013). "Depending on the severity of hypoglycemia, patient can be given glucose tablets, fruit juice, dextrose infusion, or glucagon." (PMID 24194988, 2013). "First, the proposed algorithms can coordinate the insulin and glucagon delivery simultaneously, such that more hypoglycemia can be minimized or avoided and more glucose concentrations can be kept within the normoglycemic range." (PMID 24260042, 2013). "Ward and his coworkers used the glucagon to prevent hypoglycemia in type 1 diabetes, where the fading memory proportional derivative (FMPD) algorithm was used to design the subcutaneous insulin and glucagon infusion rates." (PMID 24260042, 2013). "In high doses, glucagon can cause paradoxical insulin secretion, implying that infants receiving glucagon bolus should receive intravenous glucose infusion to prevent rebound hypoglycaemia." (PMID 23032149, 2012). "Normally, low glucose levels trigger glucagon release from α-cells to abrogate the deleterious effects of insulin-induced acute hypoglycemia." (PMID 22969729, 2012). "The production and secretion of glucagon, which enhance hepatic glucose production, are important mechanisms by which the body prevents hypoglycemia." (PMID 23316165, 2012). "Continuous subcutaneous or intravenous glucagon infusion can be initiated for refractory hypoglycaemia despite high glucose infusion rate during acute management." (PMID 23032149, 2012). "Forty years after the discovery of insulin—in 1963—an insulin pump delivering insulin and glucagon (to counteract hypoglycemia) was designed by Kadish." (PMID 24278682, 2012). "In T1D, there is a lack of decrement changes in intraislet insulin occurring which has been postulated to account for the defective glucagon counter-regulation to hypoglycemia." (PMID 22969729, 2012). "During insulin-induced hypoglycemia, glucagon raises blood glucose levels by enhancing glycogenolysis and gluconeogenesis to restore normoglycemia." (PMID 23316165, 2012). "Corticosterone in contrast to glucagon is important for hypoglycemias of longer duration, since the effects of cortisol are mainly exerted through genetic mechanisms." (PMID 22969729, 2012). "During critical illnesses, the physiological responses induced by hypoglycemia, such as the inhibition of insulin release and increased release of glucagon, epinephrine, growth hormone, and cortisol, are frequently impaired." (PMID 23062226, 2012). "This includes a glucose load and/or a glucagon injection, at the time of hypoglycemia, to correct it." (PMID 21967988, 2011). "Glucagon restores normal blood glucose levels by increasing hepatic glucose production and disruption of glucagon signalling results in hypoglycemia." (PMID 22046328, 2011). "The two main defenses to hypoglycemia are an increase in glucagon secretion and adrenaline secretion." (PMID 22214514, 2011). "Subsequent analysis of glycemic and glucagon responses to systemic glucoprivic challenge indicated that acute diminution of Bad expression in the brain is sufficient to impair hypoglycemia counterregulation." (PMID 22162752, 2011). "Insulin promotes glucose clearance from the blood when blood glucose level is high, while glucagon restores normal blood glucose level during hypoglycemia by stimulating gluconeogenesis and glycogenolysis." (PMID 22046328, 2011). "Recent studies have demonstrated success in preventing nocturnal hypoglycemia using continuous infusion and slow-release depot formulations of very low dose glucagon." (PMID 20418955, 2010). "We have shown that GE, as well as GI, neurons are impaired under conditions where both epinephrine and glucagon responses to hypoglycemia are impaired." (PMID 22022208, 2010).
Hypoglycemia (continued). "As the blood glucose level approaches normal, the amounts of insulin released and glucagon suppressed diminishes thus tending to prevent an overshoot and subsequent hypoglycemia which is seen with some other oral hypoglycemic agents." (PMID 19619327, 2009). "At the other extreme, the recent ADA consensus has defined any glucose concentration of < 3.9 mmol/l as hypoglycaemia, based on the reduction in endogenous insulin and increase in pancreatic glucagon which can be demonstrated at this level." (PMID 18215172, 2008). "Despite having hypoglycemia, the Gnasxl knockout mice show reduced glucagon levels and inappropriately normal serum catecholamine and cortisol levels, suggesting a possible impairment of the physiological responses to hypoglycemia." (PMID 19412439, 2007). "Gluconeogenesis is abolished by deletion of Bmal1 and is depressed in Clock mutants, but the counterregulatory response of corticosterone and glucagon to insulin-induced hypoglycaemia is retained." (PMID 15523558, 2004). "The actions of insulin and glucagon must be finely balanced, because both lower than normal blood sugar levels (i.e., hypoglycemia) and higher than normal blood sugar levels (i.e., hyperglycemia) can have deleterious effects on the body." (PMID 15706798, 1998). "Detailed analyses demonstrated that although the glucagon and epinephrine responses to hypoglycemia were unaffected, the growth hormone and cortisol responses were reduced after alcohol consumption." (PMID 15706798, 1998). "Rapid and specific glucagon detection is essential, particularly during hypoglycemia." (PMID 41516388, 2026). "Our results may be taken as disappointing in terms of using GLP-2 physiology as a glucagonotropic safeguard against hypoglycemia." (PMID 41541287, 2026). "Beyond its effects on the counterregulatory response to hypoglycemia, glucagon dysregulation in T2D may have other effects, including hyperglucagonemia, which can worsen blood glucose control." (PMID 41502124, 2026). "However, during hypoglycemia, a trend toward increased bsAUC of glucagon during GLP-2 infusion was seen, with only 2 participants showing a higher bsAUC during placebo." (PMID 41541287, 2026). "Furthermore, persons related to diabetic patients should also be given knowledge about glucagon use to help manage episodes of hypoglycemia." (PMID 40585626, 2025). "The diagnosis of CHI was established based on persistent severe hypoglycemia, inappropriately elevated insulin and C-peptide levels during hypoglycemia, absence of ketogenesis, a positive glucagon stimulation test, and exclusion of other causes of NH." (PMID 40904956, 2025). "We also observed decreased expression of gcgb (glucagon b) in mutants, consistent with reports of lower glucagon immunoreactivity and impaired glucagon secretion during hypoglycemia in a TS mouse model and possibly contributing to life-threatening hypoglycemia episodes in patients." (PMID 40568156, 2025). "This study represents the first demonstration of a glucose‐responsive glucagon‐releasing microneedle patch for hypoglycemia prevention, highlighting its potential to reduce the risks associated with intensive insulin therapy and improve the quality of life for diabetic patients and their caregivers." (PMID 39887601, 2025). "Hypoglycemia triggers the autonomic system, inducing an avalanche of actions, including the release of epinephrine, stimulating glucagon secretion, enhancing blood flow to the brain to prevent neuroglycopenia, and promoting gluconeogenesis in the liver to restore blood glucose levels." (PMID 41214779, 2025). "Furthermore, there was a significant degree of heterogeneity in the intervention, particularly regarding participants’ levels of education about hypoglycemia management and their familiarity with glucagon injection techniques." (PMID 40364253, 2025).
Hypoglycemia (continued). "Notably, infected GRiKO mice exhibited increased glucagon levels, while insulin levels remained unchanged, indicating that the observed hypoglycemia is insulin-independent." (PMID 40702267, 2025). "This patient subsequently reported fear of hyperglycemia based on the misdiagnosis of diabetic neuropathy and gave repeated boluses, resulting in overnight severe hypoglycemia; the patient was given glucagon nasal spray by his guardian and taken to the emergency department (ED)." (PMID 41283065, 2025). "For T3cDM, characteristic parameters include the following: rare ketoacidosis, mild hyperglycemia, common hypoglycemia, increased peripheral insulin sensitivity, decreased hepatic insulin sensitivity, insulin, glucagon, PP and GIP levels are low, and any typical age of onset." (PMID 39859258, 2025). "The patients received a personalized management plan for hypoglycaemia, which included the use of glucose powder and intramuscular glucagon for refractory cases, as well as guidance on addressing pump malfunctions, which entailed seeking hospital care for glucose stabilization." (PMID 41084516, 2025). "In this era of ongoing research to refine glucagon formulations and delivery methods, these advances may ultimately lead to a revolutionized approach to hypoglycemia management, allowing patients to be treated safely and effectively in diverse environments." (PMID 41510436, 2025). "Additionally, recurrent hypoglycemia can impair or eliminate the glucose counter-regulatory mechanism, resulting in decreased secretion of glucose-elevating hormones (such as glucagon and epinephrine) and reduced hepatic glucose production." (PMID 41573194, 2025). "Moreover, this hypoglycemia/insulin-induced copeptin and glucagon elevation is notably attenuated in individuals with type 1 diabetes (T1D) compared to non-diabetic BMI and age-matched controls." (PMID 40428796, 2025). "AVP also plays an important role in regulating glucagon secretion during hypoglycemia." (PMID 40428796, 2025). "Dasiglucagon is a glucagon analog for the treatment of hypoglycemia." (PMID 39584500, 2025). "Second, exposure was determined from claims data; actual CGM or SMBG use was unknown, and some patients may have used CGM out of pocket or treated hypoglycemia at home with glucagon." (PMID 41329488, 2025). "The clinical relevance of the delay in cortisol response to acute hypoglycemia may be limited because of glucagon and potentially the effect of catecholamines, albeit to a minor extent." (PMID 40964167, 2025). "Despite lower glucagon levels at the start of the clamp due to the known effect of incretins under euglycemic and hyperglycemic conditions, glucagon response during induced hypoglycemia was maintained with tirzepatide." (PMID 40964167, 2025). "Though only speculation, it seems that patients on LCD need higher doses of glucagon or alternative hypoglycemia rescue strategies to restore euglycemia." (PMID 40573112, 2025). "We hypothesized that an altered delta-cell architecture within the islets could also be a link partly explaining the reduced glucagon response to hypoglycemia in type 1 diabetes." (PMID 40473678, 2025). "Lower peripheral insulin levels may also help preserve glucagon response and hepatic glucose production during hypoglycemia or exercise." (PMID 40995084, 2025). "Indeed, it is worth noting that T1D is also characterized by an impaired glucagon secretion in responses to hypoglycemia, apart from exaggerated postprandial glucagon secretion." (PMID 40004833, 2025). "In addition to inhibiting hepatic glucose production, glucagon also inhibits insulin secretion from pancreatic beta-cells, thereby ensuring that glucose is available during hypoglycemia." (PMID 41510436, 2025). "Additionally, exercise-induced hypoglycemia can be challenging to prevent solely by reducing insulin doses, but adding glucagon has shown potential." (PMID 40231429, 2025).
Hypoglycemia (continued). "It should be noted that only the glucagon response to subsequent hypoglycaemia in the HIIT group was increased relative to the baseline study, with significant differences between groups resulting in part from small decrements from baseline in the control condition." (PMID 38010533, 2024). "Traditional therapies for sulfonylurea-induced hypoglycemia often involve intravenous and oral dextrose and glucagon, which may lead to recurrent hypoglycemia due to their stimulatory effects on insulin release." (PMID 39347364, 2024). "Interestingly, various studies have shown that DPP-4 inhibitors exhibit different effects depending on glucose levels: in hyperglycemia, DPP-4 inhibitors inhibit glucagon secretion, while in hypoglycemia, they enhance glucagon secretion." (PMID 39594662, 2024). "During fasting, the balance between insulin and glucagon is crucial in preventing hypoglycemia." (PMID 39149119, 2024). "Injection octreotide LAR is a commonly prescribed medication and may interfere secretion of countercurrent hormones like glucagon and worsen hypoglycemia so short-acting SSA is to be given first as a challenge." (PMID 39677350, 2024). "The inability to secrete glucagon normally when exposed to hypoglycemia in T1D may be because of intra-islet dysregulation in the absence of insulin secretion from pancreatic ß-cells and/or elevated somatostatin (SST) signalling from nearby pancreatic δ-cells." (PMID 38510652, 2024). "Increased insulin action can be demonstrated by increased glucose requirement (e.g., >8 mg/kg/min in a neonate normal 4–6 mg/kg/mi), inappropriately suppressed plasma concentrations of FFA and BOHB during hypoglycemia, and an inappropriate glycemic response to glucagon at a time of hypoglycemia." (PMID 37454648, 2024). "This is postulated to result from the increased intrahepatic glucose flux that results following gluconeogenesis and glycogenolysis in response to hypoglycemia, blocking the stimulus for α-cells lodged within hepatic sinusoids to release glucagon despite systemic hypoglycemia." (PMID 39450137, 2024). "Globally interfering with VMN function (e.g., by deleting VMN vGLUT2, thereby blocking glutamatergic signaling by VMN neurons) mediates effects opposite to those of VMN activation, impairing glucagon secretion, glycogenolysis, and hepatic transcriptional responses to hypoglycemia and during fasting." (PMID 38826340, 2024). "The use of glucagon to treat insulin-induced hypoglycemia is not expected to increase the risk of adverse pregnancy outcome." (PMID 39296666, 2024). "Various studies have shown that GLP-1 receptor agonists (GLP-1 RAs) increase post-prandial insulin release and inhibit glucagon secretion, all without the risk of hypoglycemia." (PMID 39262529, 2024). "Transitional neonatal hypoglycemia has characteristic features of hyperinsulinism, including the suppression of ketone production, the inhibition of glycogenolysis, and an exaggerated response to glucagon; it usually resolves within 36–48 h after birth." (PMID 38792494, 2024). "Reduction in glucagon levels in response to hypoglycemia have been documented in patients after GB, and those patients with PBH may have a higher degree of dysregulation." (PMID 39444516, 2024). "Since amino acids also promote the release of insulin, it is hypothesized that the purpose of the increase in glucagon release is to physiologically prevent hypoglycemia following protein consumption." (PMID 39337311, 2024). "Furthermore, there is a paradoxical impairment of glucagon secretion during hypoglycemia in patients with diabetes." (PMID 38397994, 2024). "However,at 60 mg/dL (hypoglycemia) the micelles disassembled into linear/unimericpolymers revealing the active glucagon conjugate." (PMID 39634211, 2024).
Hypoglycemia (continued). "However, VMH administration of bicuculline methiodide, a GABAA receptor antagonist, restored glucagon and epinephrine response to hypoglycemia 44 45, suggesting a possible clinical benefit of GABA antagonists as a therapeutic tool to treat IAH." (PMID 38323079, 2024). "With these objectives in mind, we successfully developed a male rodent model of late-stage T2D characterized by significantly higher HbA1c, insulin resistance and defective glucagon counterregulation to insulin-induced hypoglycemia compared to HFF and NCF controls." (PMID 38510652, 2024). "However, side effects of glucagon should also be considered while administration, such as hyperkalemia, hypoglycemia, chest pain, and headache." (PMID 39001295, 2024). "It has been suggested that increased paracrine-mediated alpha-cell inhibition by excessive basal somatostatin secretion from the delta-cells in response to low glucose may be responsible for the aberrant glucagon response to hypoglycemia in T1D." (PMID 38612880, 2024). "In response to hypoglycemia, healthy alpha cells are stimulated to release glucagon." (PMID 39594662, 2024). "Plasma glucagon increased within the first hour following ZT-01 treatment compared to controls, and remained elevated until 1 h after insulin bolus administration for hypoglycemia induction (2 h after ZT-01 dosing)." (PMID 38510652, 2024). "In this hypothesis, insulin secretion from β-cells decreases during hypoglycemia and, at the same time, serves as an activating signal for the release of glucagon from α-cells." (PMID 38397994, 2024). "Blood insulin and glucagon concentrations, which play a major role in regulating blood glucose levels, were compared pre- and postoperatively to examine the physiological responses to hypoglycemia." (PMID 38393097, 2024). "Taken together, neither lower plasma concentrations of glucocorticoids or glucagon nor a reduced systemic response to these hormones are responsible for the phenotype of aggravated insulin-induced hypoglycemia in TRPC5-deficient mice." (PMID 39375537, 2024). "Moreover, serotoninergic neurons are required for glucagon secretion, a key element of the counterregulatory response to hypoglycemia." (PMID 39264731, 2024). "They noted a significantly improved glucagon CRR to hypoglycemia in the AICAR treated diabetic rats as compared to saline treated controls indicating that AMPK manipulation could be a useful pharmaceutical tool to treat IAH." (PMID 38323079, 2024). "Three studies describe the use of newer glucagon formulations in insulin-induced hypoglycemia." (PMID 39944479, 2024). "The main biological function of glucagon is counter-balancing insulin in hypoglycemia." (PMID 39594592, 2024). "We hypothesized that treatment with an SSTR2 antagonist (PRL-2903), prior to insulin-induced hypoglycemia, would increase the glucagon response to iatrogenic (i.e., insulin-induced) hypoglycemia." (PMID 38510652, 2024). "It is secreted in response to hypoglycaemia and stimulates glucagon secretion." (PMID 38017352, 2024). "Our findings also suggest that HIIT may improve the glucagon response to insulin-induced hypoglycaemia." (PMID 38010533, 2024). "GLP-1ra enhance glycaemic control by stimulating insulin secretion and by a glucose-dependent inhibition of glucagon release, resulting in effective glucose lowering without increased risk of hypoglycaemia." (PMID 38894744, 2024). "The beneficial effect of GLP-1 on PBH may be biphasic, initially inhibitory and later becoming stimulatory of glucagon secretion during hypoglycemia." (PMID 38842763, 2024). "Experimental research in a rodent model of type 1 diabetes has shown that the glucagon response to insulin-induced hypoglycaemia can be enhanced by activation of key hypothalamic glucose-sensing regions, which in turn amplify the autonomic response to hypoglycaemia." (PMID 38010533, 2024).